ALK (ALK receptor tyrosine kinase)
Diseases named in the same sentence as ALK in open-access papers (continued):
Sharing a sentence is not in itself a finding about the gene and the disease.
tumor (continued). "When exposed to ALK-TKIs, a small fraction of cells survives and expands, leading to acquired drug resistance and tumor heterogeneity, eventually promoting tumor recurrence." (PMID 36702855, 2023). "The sensitivity to ALK-targeted therapy was demonstrated with prolonged disease stabilization of the previously rapidly progressing disease and extensive tumor necrosis in the autopsy." (PMID 38096470, 2023). "The Children’s Oncology Group pilot trial ANBL12P1 (NCT01798004) demonstrated the logistical feasibility of obtaining ALK status within 21 days of receiving a tumor sample." (PMID 37835416, 2023). "Basic studies have shown that the ATR inhibitor (BAY1895344) combined with the ALK inhibitor (lorlatinib) can lead to complete regression of tumor cells in an ALK‐driven NB mouse model." (PMID 38090056, 2023). "Human tumor samples of ALK+ NSCLC were acquired from the Auria Biobank (Turku, Finland) under study number BB_2020–0045." (PMID 37722715, 2023). "Envonalkib, a novel ALK inhibitor, demonstrated promising anti-tumor activity and safety in advanced ALK-positive NSCLC in the first-in-human phase I study." (PMID 37574511, 2023). "For example, NSCLC patients with PD-L1 tumor proportion score (TPS) ≥ 50% seem to benefit from immunotherapy, but for those carrying EGFR-sensitive mutations and ALK rearrangements (EGFR+/ALK+), the response to immunotherapy appears to be poor." (PMID 37266427, 2023). "We provided evidence that this interaction is present in vitro by two methods (IP and PLA) and in vivo using human ALK-translocated tumor samples." (PMID 37722715, 2023). "TGI metrics were estimated from a biexponential model using longitudinal tumor size data from a Phase 3 study evaluating alectinib compared with crizotinib in patients with treatment-naive ALK-positive advanced NSCLC." (PMID 37410154, 2023). "This case highlights the importance of careful examination of cell morphology, even if CD30 and ALK expression in circulating tumor cells is low." (PMID 38136278, 2023). "ALK-driven NB patients usually have a poor prognosis and ALK activity is highly correlated to aggressive tumor progression, metastasis and chemotherapy resistance." (PMID 38264745, 2023). "Another report described preoperative treatment using the neoadjuvant ALK inhibitor crizotinib for tumor reduction of locally advanced IMT of the bladder, enabling bladder-preserving surgery without recurrence." (PMID 37656266, 2023). "In these patients, the estimated proportion of detectable ctDNA in the cell-free DNA comprehensive tumor fraction (CTF) followed the same trend as the ALK VAF." (PMID 37147298, 2023). "Genetic or pharmacologic disruption in the NPM::ALK-ACLY signaling axis leads to impaired cell proliferation, impaired clonogenic potential, reduced tumor growth in an in vivo xenograft model, and attenuated lipid synthesis in ALK+ ALCL." (PMID 37810974, 2023). "PDGFR-α, PDGFR-β, c-Kit, FGFR1, and anaplastic lymphoma receptor tyrosine kinase (ALK) were overexpressed in the tumour tissues compared with their levels in normal tissues." (PMID 38332765, 2023). "All ALK inhibitors were solely been indicated for patients with ALK-positive tumours (defined by a validated method), whereas EGFR inhibitors (specifically erlotinib) were also used to some extent outside of EGFR-positive patients." (PMID 36900294, 2023). "With few options remaining, crizotinib was selected as a therapeutic/palliative target based on the increased levels of ALK protein expressed in the patient's tumor." (PMID 36619485, 2023). "Fusions and mutations of anaplastic lymphoma kinase (ALK), a tyrosine kinase receptor, have been identified in several neoplastic diseases." (PMID 37954850, 2023).
tumor (continued). "In this study, the ALK mutation group had higher edema/tumor ratio (5.66 ± 21.15) than KRAS (5.08 ± 8.70) and EGFR (2.38 ± 6.13) positive mutation groups, implicating worse survival in the ALK mutation group." (PMID 37508989, 2023). "The combinatorial therapy of YAP1 with ALK inhibitors showed tumour remission in ALK‐rearranged xenografts." (PMID 37149843, 2023). "Using cell lines harboring various targetable kinase gene fusions, the limit of detection was determined to be 10% tumor cell content for ALK, ROS1, and RET rearrangements." (PMID 37628603, 2023). "In a representative case, we analyzed 22 tumor cells, recognized based on their morphology and ALK expression." (PMID 37762644, 2023). "NPM::ALK also modulates cancer metabolism through the downregulation of CD147, causing aberrant glycolysis and thus impairing the major energy source of tumor cells." (PMID 37810974, 2023). "NVP.TAE684 is an ALK inhibitor that inhibits ALK rearrangement and the downstream related signaling pathways, resulting in tumor cell proliferation and survival." (PMID 37665670, 2023). "This alteration leads to the uncontrolled growth and spread of the tumor cells, which is a crucial reason why ALK-positive NSCLC is more aggressive and resistant to traditional chemotherapy treatment than NSCLC without this alteration." (PMID 37409244, 2023). "Further investigations regarding the mechanism of tumor development, imaging findings for early detection, and the optimum treatment are essential for ALK-positive IMT." (PMID 37656266, 2023). "Next generation sequence testing confirmed the presence of the intergenic region (chr2: 30,193,816)-ALK fusion in the tumor tissue." (PMID 36755262, 2023). "Then, next-generation sequencing on circulating tumor DNA identified multiple ALK mutations, including ALK G1202R, I1171N, ALK-ENC1, and EML4-ALK." (PMID 37007089, 2023). "A previous study reported that a significant number of PD-1-positive CD8+ T cells infiltrated the ALK-positive tumour bed." (PMID 37371571, 2023). "In multivariate analysis after PSM, thoracic tumor radiotherapy, radiotherapy, N0‐2, and ALK‐ TKIs predicted longer OS." (PMID 37288833, 2023). "Seventy-nine children (aged 6 years or older) and adolescents were enrolled; tumor responses were more pronounced among patients with tumors with activating ALK aberrations." (PMID 36839989, 2023). "Histological lesions and neoplasms should be assessed for ALK immunostaining, particularly in cases of multiorgan involvement and in those instances where the lesions are not amenable to resection." (PMID 36915094, 2023). "Vaccination of mice significantly increased the number of tumour‐infiltrating T lymphocytes specific for ALK, compared with mice injected with EML4‐ALK tumour cells." (PMID 37795653, 2023). "Recently, our group reported a case of PDGFRA-mutant GIST with ALK expression, in which the tumor had an immense size, and follow-up revealed liver metastases that developed quickly." (PMID 37120571, 2023). "Effective control of tumor growth can beachieved by dose-dependent inhibition of tyrosine phosphorylation of MET kinaseand ALK." (PMID 39077026, 2023). "Cytologically, ALK− ALCL cells demonstrate similarities with ALK+ ALCL in terms of appearance; however, small tumor cells typically found in ALK+ ALCL variants involving small-cell and lymphohistiocytic subtypes should not be evident in ALK− ALCL cases." (PMID 37443818, 2023). "Pathological examination revealed that the pulmonary tumours were common type ALK+ALCL that consisted of only large‐sized tumour cells despite alectinib administration." (PMID 36819147, 2023). "We generated tumor cell cultures from multiple regions of an ALK‐rearranged clinical tumor specimen and deployed functional drug screens to identify modulators of ALK‐inhibitor response." (PMID 36423211, 2023).
tumor (continued). "The segmentation accuracy for each class is evaluated to conclude a treatment prescription focusing on ALK-positive and ALK-negative tumor diversity." (PMID 36826944, 2023). "Only a proportion of PTCL, NOS cases expressed pSTAT3-Y705 (5/34, 15%) and pSTAT3-S727 (16/34, 47%) in more than 70% tumor cells (p<0.001 compared to ALK+ and ALK- ALCL)." (PMID 37388733, 2023). "Despite marked anti-tumor efficacy observed both in preclinical settings and in the clinic, acquired resistance to ALK TKIs inevitably occurs during the course of treatment." (PMID 38264745, 2023). "APG-2449 is a novel FAK inhibitor and a third-generation ALK/ROS1-TKI that has shown potent activity towards a range of ALK-resistant mutations and brain penetrant capacity in pre-clinical NSCLC tumor models." (PMID 37894445, 2023). "A total of 33 other studies were further excluded because they did not include relevant information such as implant substitution or the associated immunophenotype of tumor cells (i.e., CD30 and ALK protein expression)." (PMID 37927474, 2023). "Co-localization of ALK and HER3 was investigated by immunoprecipitation (IP) and proximity ligation assay (PLA) in vitro and in vivo using six ALK+ NSCLC tumor samples." (PMID 37722715, 2023). "Immunohistochemistry staining showed that both pSTAT3-Y705 and -S727 were highly expressed in the nuclei of tumor cells in both ALK+ and ALK- ALCL, with diffuse and intense staining." (PMID 37388733, 2023). "In patient-derived xenografts harbouring the common activating ALK mutations (F1174L, F1245C), combinatorial ALK (ceritinib) and PIM1 (AZD1208) inhibition displayed greater anti-tumour efficacy than either agent in isolation." (PMID 37414143, 2023). "In so doing, ALK promotes malignant cell survival to protect tumor cells from drug-induced genotoxic stress." (PMID 36253486, 2022). "Another study showed that most tumours with V3 harbour both V3a and V3b RNA isoforms, and that treatment with ALK TKIs increases the proportion of V3a relative to V3b over time." (PMID 35884511, 2022). "The majority of ALK+ ALCL tumor cells have been shown to express at least one T-cell specific marker." (PMID 35246138, 2022). "Activating mutations were identified in tumor samples including EGFR L858R, EGFR T790M, EGFR exon 19 deletion, ERBB2 amplification, ALK fusion, KRAS G12C." (PMID 35123506, 2022). "Morphologically, ALK− ALCL is similar to the common pattern of ALK+ ALCL, with the presence of hallmark cells, and frequently exhibits a cohesive sheet of large tumor cells with irregular nuclei and sinusoidal involvement." (PMID 36010351, 2022). "CD147 knockdown in ALK+ ALCL cells resulted in loss of monocarboxylate transporter 1 (MCT1) expression, reduced glucose consumption and tumor growth retardation, as demonstrated by [18F]FDG-PET/MRI analysis." (PMID 35676454, 2022). "In vitro and in vivo tests with ALK inhibitors showed pre-clinical evidence for tumor reduction in a PPP1CB–ALK positive tumor as a response to ALK targeted therapy with lorlatinib." (PMID 35169893, 2022). "Compared with ALK-TKIs alone, cotreatment with pan-HER inhibitor afatinib and ALK-TKIs prevented tumor regrowth, leading to the eradication of tumors in ALK-rearranged tumors with mesenchymal features." (PMID 35042943, 2022). "We obtained NSCLC tumor biopsies from 11 patients with EML4-ALK rearrangements before and/or after ALK inhibitor therapy." (PMID 35999456, 2022). "The development and application of ALK inhibitors have made outstanding contributions to the treatment of ALK+ tumor patients, and it is still the main choice for first-line treatment." (PMID 35958559, 2022). "Specifically, we found that the WNT signaling cell surface receptor ROR2 represented a robust and genuine marker of all ALK+ ALCL patient tumor samples." (PMID 35246138, 2022).
tumor (continued). "It is also possible to detect potentially actionable activating genetic abnormalities specific to primary tumours (e.g., EGFR gene mutations or ALK and ROS1 gene rearrangements in patients with NSCLC)." (PMID 35884492, 2022). "We now confirmed CD147 as miR-146a direct target gene and demonstrate that functional CD147-MCT1 transmembrane complexes are necessary for cellular metabolism supporting tumor growth, angiogenesis, and invasion in vitro and in vivo in ALK+ ALCL cells." (PMID 35676454, 2022). "Through the dimerization of the coiled-coil domain, the activity of ALK tyrosine kinase is abnormally activated, resulting in the occurrence of tumor." (PMID 36290895, 2022). "Accordingly, cfDNA from liquid biopsies and DNA from matched tumour samples of high-risk NB patients were collected and used to detect MYCN amplification and actionable ALK genetic alterations." (PMID 36362869, 2022). "Because of the absence of the major substrate of CD45, LCK, it is plausible that in ALK+ ALCL the CD45 phosphatase activity affects the JAK/STAT pathway therefore playing a role as a tumor suppressor." (PMID 36698412, 2022). "The anti-ALK CTL generated from the PBL of healthy donors induces an antigen-specific HLA-A2.1 restricted response, which can effectively kill endogenous ALK-expressing tumor targets." (PMID 35958559, 2022). "XMU‐MP‐5 showed substantial activity against G1202R in vitro, with an IC50 value of 49 nM, and it significantly inhibited ALK(G1202R) Ba/F3 tumor growth in the xenograft mouse model." (PMID 34845836, 2022). "Halpenny’s study showed that ALK-positive tumours tended to be more prominent with more solid consistency and involved more thoracic lymphadenopathy." (PMID 35406429, 2022). "The requirement of ACT therapy for the hypermutability of the tumor cells themselves and for hyperresponsiveness to immunotherapy, indicates the potential significance of ALK rearranged NSCLC to this therapy." (PMID 36591504, 2022). "A recent retrospective analysis of ALK autoantibody concentrations in patients with ALCL found that patients with high titer of anti ALK autoantibodies had longer survival and that ALK autoantibody levels inversely correlated with tumor recurrence." (PMID 36591504, 2022). "We identified tumor-derived 5-mC signals in 92.4% (61/66) of cfDNA samples and 90.5% (19/21) of ALK-positive patients." (PMID 36461127, 2022). "The anti-tumor mechanism of ALK-i is related to their activity as ATP analogue inhibitors of ALK, because of their binding to the ATP-binding pocket of the intracellular tyrosine kinase domain." (PMID 36230686, 2022). "A screen of tumors from ALK+ ALCL patients who progressed within 3 months of crizotinib treatment found that IL-10RA was overexpressed in tumor cells, leading to ALK TKI resistance." (PMID 35211406, 2022). "In pediatric populations, crizotinib has been investigated in a variety of solid tumors and anti-tumor activity has been correlated with the presence of ALK aberrations." (PMID 36034555, 2022). "ALK IHC (clone 5A4, Novocastra) showed strong cytoplasmic staining of tumor cells in both LCNEC and ACA components." (PMID 35200571, 2022). "This was a phase 1 study (NCT02695550) to determine the safety, maximum tolerated dose (MTD), pharmacokinetic (PK), and anti-tumor activity of conteltinib in patients with advanced ALK-positive NSCLC." (PMID 36424628, 2022). "No targetable driver mutations (epidermal growth factor receptor [EGFR], anaplastic lymphoma kinase [ALK] and ROS‐1) and a programmed death‐ligand‐1 (PD‐L1) tumour proportion score of 25%–49% were shown." (PMID 35822082, 2022). "Lastly, these emerging data confirm that ALK is a compelling therapeutic target, as demonstrated by its role as an oncogenic driver in several tumor types of different lineages, including RCC." (PMID 35409355, 2022). "The overexpression of ALK activates the downstream transcription factor STAT3 and thus increases PD-L1 expression in ALK+ALCL tumor cells." (PMID 35884893, 2022).
tumor (continued). "EML4-ALK exhibits potent oncogenic properties both in vitro and in vivo, in which tumor development can be rapidly suppressed using ALK TKIs." (PMID 35620280, 2022). "The histological examination combined with immunohistochemistry proved IMT, and the ALK fluorescence in situ hybridization examination found ALK translocation in 38% of the tumor cells." (PMID 36550868, 2022). "Rearrangement of ALK accounts for 4%–7% of NSCLC patients, only second to EGFR mutation, which promotes the growth and proliferation of malignant tumor cells." (PMID 35734411, 2022). "The results showed that 60% (252/422) of the tumor tissues had driver mutations, including 107 cases of KRAS (25%), 98 cases of EGFR (23%), 14 cases of ALK rearrangement (6%)." (PMID 35433677, 2022). "The observations from our study should be validated in larger studies in patients with a de novo diagnosis of metastatic ROS1‐ and ALK‐rearranged NSCLCs to control for lead time bias and for more comprehensive tumor molecular typing." (PMID 35510711, 2022). "XMU‐MP‐5 blocks ALK signaling pathways and inhibits the proliferation of cells harboring either wild‐type or mutant EML4‐ALK in vitro and suppresses tumor growth in xenograft mouse models in vivo." (PMID 34845836, 2022). "Recently, research targeting anti ALK antibodies is constantly being explored, and some newly developed monoclonal antibodies against ALK have been confirmed to inhibit the growth of ALK positive tumor cells in in vitro experiments." (PMID 36591504, 2022). "In our patient cohort, the detection of targetable tumor alterations (EGFR mutation and ALK fusion) has led to treatment with EGFR/ALK specific tyrosine kinase inhibitor in all stage IV patients according to the present-day recommendations." (PMID 35108331, 2022). "IHC staining further showed that XMU‐MP‐5 induced tumor remission by inhibiting ALK activity and inducing tumor cell apoptosis." (PMID 34845836, 2022). "ALK alterations were detected with different procedures either in neoplastic tissue provided by biopsies of distant RCC metastases or circulating tumor DNA (ctDNA)." (PMID 35409355, 2022). "One patient presented with multiple metastases to the subcutaneous tissue and bone that responded to ALK inhibitor alectinib therapy, and the tumor was observed to regress 10 months after the initial ALK inhibitor therapy." (PMID 35280868, 2022). "Recent discoveries pointed out that these neoplasms, with a clinical course that differs from their pediatric and adult counterparts, carry specific molecular alterations, namely kinase (ALK, NTRK1/2/3, ROS1, or MET) gene fusions." (PMID 35565372, 2022). "The ALK-positive tumor showed a Gleason score of 4+4 = 8 with extensive large cribriform morphology." (PMID 36337169, 2022). "In order to investigate the downstream targets of the tumor suppressor miR-146a, ALK+ ALCL cell lines were transfected with miR-146a mimic and analyzed using RNA-seq analysis." (PMID 35676454, 2022). "Use of this antibody demonstrated NPM-ALK protein to be present at high levels in ALCL resulting in the identification the new tumour entity ALK-positive ALCL." (PMID 35011737, 2022). "Two hundred and forty-five of 829 (29.6%) DMRs were concordantly hypermethylated in ALK-positive cfDNA and tumor tissue samples, and the significance of overlaps was confirmed by permutation testing (p < 0.0001)." (PMID 36461127, 2022). "In this study, we aimed to identify the downstream targets of miR-146a, a tumor suppressor miRNA in ALK+ ALCL." (PMID 35676454, 2022). "Anti ALK antibodies against ALK-WT and ALK fusions can specifically attack ALK positive tumor cells, contributing to the inhibition of tumor growth." (PMID 36591504, 2022). "Currently routine clinical molecular testing in relation to druggable fusion genes is limited to NSCLC, but even in this tumour type, analysis covers only a small number of potential driver and partner genes, namely ALK and ROS rearrangements." (PMID 35984852, 2022).